TUFT1 (tuftelin 1)
Diseases named in the same sentence as TUFT1 in open-access papers (continued):
Sharing a sentence is not in itself a finding about the gene and the disease.
ovarian carcinoma (4 papers, 2021 to 2024). A malignant neoplasm originating from the surface ovarian epithelium. "Thus, it seems that screening diagnosis of ovarian cancer should be supplemented by GLO1, TUFT1, and UBA2 determination and assessment of the risk of loss of adequate response to chemotherapy by GLO1 mRNA expression pattern determination." (PMID 35992817, 2022). "Thus, we speculate that TUFT1 may serve as a complementary molecular marker in differentiating the clinical stage of ovarian cancer." (PMID 35992817, 2022). "Moreover, we observed an increase in the mRNA and protein expression of TUFT1 in group A as compared with the control group and group B. However, we did not confirm that changes in the TUFT1 expression profile depend on the occurrence of drug resistance to platinum compounds in ovarian cancer." (PMID 35992817, 2022). "We noted that the mRNA of UBA2, GLO1, TUFT1, HPD, and GBF1 were upregulated in the ovarian cancer samples in comparison to the control samples." (PMID 35992817, 2022). "mRNAs corresponding to genes UBA2, GLO1, STATH, and TUFT1, were differentiated in the study samples, irrespective of the stage of ovarian cancer from the control samples, and we decided to focus on them in further analyses." (PMID 35992817, 2022).
triple-negative breast carcinoma (4 papers, 2019 to 2025). An invasive breast carcinoma which is negative for expression of estrogen receptor (ER), progesterone receptor (PR), and human epidermal growth factor receptor 2 (HER2). "Actually, TUFT1 could induce invasion of triple negative breast cancer in a dose-dependent manner." (PMID 36797791, 2023). "We performed immunohistochemical analysis of triple-negative breast cancer (TNBC) tissue microarrays and assessed the correlation between NEK2/TUFT1 expression and patient outcome." (PMID 41022752, 2025).
colorectal cancer (3 papers, 2022 to 2025). A primary or metastatic malignant neoplasm that affects the colon or rectum. "The miR-214-3p-TUFT1 axis is closely related to liver metastasis and the maintenance of tumor stem cell characteristics in colorectal cancer." (PMID 41217541, 2025). "who found that overexpression of TUFT1 mRNA and protein is characteristic for identifying higher clinical stages of colorectal cancer (stages III and IV) and development of vincristine resistance through the PI3K/AKT pathway." (PMID 35992817, 2022).
dental fluorosis (3 papers, 2019 to 2023). A condition that results from excessive fluoride ingestion during tooth development, resulting in tooth discoloration ranging from white streaks to brown stains and cracks or pits in the tooth enamel. "These teams analyzed TUFT1 rs4970957 and miRNA17 rs4284505, indicating that alleles A and G increased the risk of dental fluorosis." (PMID 36354656, 2022).
amelogenesis imperfecta (2 papers, 2009 to 2025). Amelogenesis imperfecta (AI) represents a group of developmental conditions affecting the structure and clinical appearance of the enamel of all or nearly all the teeth in a more or less equal manner, and which may be associated with morphologic or biochemical changes elsewhere in the body. "For some other genes encoding for enamel matrix proteins, e.g. ameloblastin (AMBN 4q 11), tuftelin (TUFT1 1q 21) and amelotin (4q 13.3) mutations have not yet been identified in patients with amelogenesis imperfecta." (PMID 19913215, 2009).
lung adenocarcinoma (2 papers, 2018 to 2023). A carcinoma that arises from the lung and is characterized by the presence of malignant glandular epithelial cells. "Particularly in the patients with stage I lung adenocarcinoma, TUFT1 expression was more significantly associated with poor prognosis." (PMID 29423269, 2018). "In NCI-H441 lung adenocarcinoma cells, TUFT1 was shown to be a novel target of transforming growth factor-β1 (TGF-β1) and exhibited a pivotal involvement in the orchestration of microfilament formation within A549 cells." (PMID 38105232, 2023). "By analyzing data from chromatin immunoprecipitation-based sequencing using antibodies against TTF-1 and SMAD325, we identified TUFT1 as a direct target of transforming growth factor β (TGF-β) which was inhibited by TTF-1 in NCI-H441 lung adenocarcinoma cells." (PMID 29423269, 2018). "We observed high expression of TUFT1 in TTF-1-negative A549 lung adenocarcinoma cells compared to TTF-1-positive NCI-H441 cells; furthermore, TUFT1 expression was strongly induced by TGF-β and the protein was located mainly in the cytoplasm." (PMID 29423269, 2018). "Research has demonstrated that TUFT1 can be induced to express as a direct target of TGF-β1, and TUFT1 can influence the formation of F-actin in lung adenocarcinoma cells." (PMID 38105232, 2023). "We showed here that depletion of TUFT1 or RABGAP1 alleviated the accumulation of transport vesicles and lysosomes, which led to mTORC1 inactivation and tumor regression in A549 lung adenocarcinoma cells." (PMID 29423269, 2018).
lymph node metastasis (2 papers, 2017 to 2025). "We found that patients with high NEK2 and TUFT1 expression had a significantly high rate of lymph node metastasis, reflecting poor outcome." (PMID 41022752, 2025).
renal cell carcinoma (2 papers, 2021 to 2023). "However, the involvement of TUFT1 in renal cell carcinoma (RCC) remains unknown." (PMID 34257606, 2021).
Cirrhosis (1 paper, 2022). A chronic disorder of the liver in which liver tissue becomes scarred and is partially replaced by regenerative nodules and fibrotic tissue resulting in loss of liver function. "We also analyzed GSE54238 which contains inflammatory, cirrhosis, early HCC, and late HCC samples and found that TUFT1 was increased both in early HCC and late HCCs but not in inflammatory or cirrhosis tissues." (PMID 35769513, 2022).
COVID-19 (1 paper, 2026). A disease caused by infection with severe acute respiratory syndrome coronavirus 2. "Gene-level association analysis revealed MTERF1, TUFT1 (encoding Tuftelin1), and RETSAT (encoding retinol saturase) as the most significantly associated genes, all enriched for LoFs in patients with COVID-19." (PMID 41500120, 2026).
fibrosis (1 paper, 2023). the formation of excess fibrous connective tissue in an organ or tissue in a reparative or reactive process. "Our results demonstrated a significant upregulation of TUFT1 in IPF and the bleomycin (BLM)-induced fibrosis model." (PMID 38105232, 2023).
head-neck squamous cell carcinoma (1 paper, 2025). "Contrastingly, in some other cancers, such as stomach adenocarcinoma and head-neck squamous cell carcinoma, patients with hypophosphorylated TUFT1 exhibited reduced OS." (PMID 41022752, 2025).
hyperlipidemia (1 paper, 2021). "Another study showed that genes, including the TUFT1 gene, were differentially expressed in liver cells from hyperlipidemia mice under treatment with red raspberry extract." (PMID 34567069, 2021).
liver cancer (1 paper, 2022). An epithelial or non-epithelial malignant neoplasm that arises from the liver. "In all three datasets the expression levels of PEA15, PPP1CA and TUFT1 were significantly increased in liver cancer tissue compared to adjacent non-tumorous liver tissue." (PMID 34976171, 2022).
lung carcinoma (1 paper, 2021). "However, in lung cancer cells, TUFT1 seems to enhance tumorigenesis through mTORC1 signaling pathway." (PMID 34257606, 2021).
prostate carcinoma (1 paper, 2019). A carcinoma that arises from epithelial cells of the prostate gland. "Consistent with Casodex preventing expression of some potentially harmful isoforms in prostate cancer cells, the splicing inclusion of NUMB exon three and TUFT1 exon two were reduced by Casodex (both these exons are normally activated by androgen exposure and ESRP2)." (PMID 31478829, 2019).
pulmonary fibrosis (1 paper, 2023). Chronic progressive interstitial lung disorder characterized by the replacement of the lung tissue by connective tissue, leading to progressive dyspnea, respiratory failure, or right heart failure. "To investigate the role of TUFT1 in pulmonary fibrosis, we examined fibrotic responses after the silenced TUFT1 expression by using Adeno-associated virus knockdown of TUFT1 (Tuft1/short hairpin RNA (shRNA)) in bleomycin-induced mouse pulmonary fibrosis model." (PMID 38105232, 2023). "The benefits observed in reducing lung fibrosis in mice via TUFT1 interference are likely associated with its impact on F-actin expression, primarily involving the assembly process from G-actin to F-actin." (PMID 38105232, 2023). "Altogether, these data indicate that inhibition of TUFT1 alleviated bleomycin-induced experimental models of lung fibrosis." (PMID 38105232, 2023). "Genetic silencing of TUFT1 mitigated bleomycin-induced lung fibrosis and concurrently reduced the bleomycin-induced increase in F-actin in mice." (PMID 38105232, 2023). "Meanwhile, the levels of Fibronectin and collagen I was decreased by Tuft1/shRNA in pulmonary fibrosis process." (PMID 38105232, 2023). "We investigated the level of TUFT1 in the IPF and bleomycin-induced mouse models and explored the influence of TUFT1 deficiency on pulmonary fibrosis." (PMID 38105232, 2023). "Our findings suggested that TUFT1 plays a critical role in pulmonary fibrosis via its influence on stress fiber, and blockade of TUFT1 effectively reduces pro-fibrotic phenotypes." (PMID 38105232, 2023). "In both IPF patients and a murine model of bleomycin-induced lung fibrosis, we observed a significant upregulation of TUFT1." (PMID 38105232, 2023). "These evidences suggest that TUFT1 likely affects pulmonary fibrosis by influencing the assembly of F-actin." (PMID 38105232, 2023). "We found a positive correlation between F-actin expression and the extent of lung fibrosis, with both showing consistent alterations with TUFT1." (PMID 38105232, 2023). "Interestingly, the Phalloidin staining revealed a marked abundance of F-actin within the fibrotic tissues of the bleomycin-induced lung fibrosis model, whereas the Tuft1/shRNA led to a reduction in F-actin formation in bleomycin-challenge lung tissues." (PMID 38105232, 2023). "Our investigation delved into the role that TUFT1 plays in experimental lung fibrosis in mice." (PMID 38105232, 2023). "Additionally, we explored the effect of TUFT1 on the cytoskeleton and illustrated the relationship between stress fiber and pulmonary fibrosis." (PMID 38105232, 2023). "Disruption of TUFT1 exerted inhibitory effects on pulmonary fibrosis in both in vivo and in vitro." (PMID 38105232, 2023). "This research marks a preliminary foray into understanding the role of TUFT1 in fibrotic diseases, introduces a novel pathogenic mechanism in the realm of IPF research, and evaluates the potential of N-WASP-F-actin as a therapeutic target for combating pulmonary fibrosis." (PMID 38105232, 2023).
tumor (16 papers, 2017 to 2026). "Following analysis of patient clinicopathological parameters showed that TUFT1 expression was closely associated with HCC tumor size, vascular invasion, and tumor differentiation." (PMID 35769513, 2022). "Although we do not know the reason regarding the TUFT1 expression difference, we suspect that TUFT1 expression is associated with RCC tumor stage." (PMID 34257606, 2021). "In conclusion, our results illustrate the essential role of TUFT1 in the regulation of tumor progression through centrosome number control, implying that TUFT1 may be a promising target for diagnostic and therapeutic approaches for cancers." (PMID 41022752, 2025). "In addition, HeLa cell lines corresponding to TUFT1 mutations were subcutaneously injected into female nude mice to induce ectopic tumor formation." (PMID 41022752, 2025). "Moreover, TUFT1 loss suppressed tumor sphere formation and stemness-related factors expression." (PMID 37986103, 2023). "In addition, although it is beyond the scope of the current study, it would be warranted to investigate whether TUFT1 promotes tumor progression in other types of solid cancers and underlying mechanisms." (PMID 34257606, 2021). "In HSC/CRC co-implantation and portal vein tumor injection mouse models, targeting TUFT1 of HSCs inhibited HSC activation and restricted CRC growth in both subcutaneous and hepatic sites." (PMID 41593321, 2026). "Overall, these results reveal a crucial role of TUFT1 in the regulation of tumor progression through centrosome number control." (PMID 41022752, 2025). "Among them, GABBR2 and TUFT1 exhibited high expression levels in tumor tissues, whereas SPEF2 demonstrated low expression." (PMID 41217541, 2025). "Overexpression of PEA15, PPP1CA and TUFT1 and a related poorer outcome have also been observed in other tumor entities 35-37." (PMID 34976171, 2022). "Of the 2 cases in our study showing lower TUFT1 expression than the rest of the cases, they are both in the early tumor stage (TNM stage T1 and T2, respectively)." (PMID 34257606, 2021). "In the current study, we used signaling pathway inhibitors to determine the signaling pathway that is involved in TUFT1-enhanced RCC tumor progression." (PMID 34257606, 2021). "Similar difference in TUFT1 expression is also observed in HCC, which is reported to be associated with HCC tumor stage as well." (PMID 34257606, 2021). "A nude mouse xenograft tumor model revealed that TUFT1 knockdown greatly decreased spontaneous lung metastasis of TNBC tumors." (PMID 31338333, 2019). "Here, we demonstrated that TUFT1 knockdown can reverse doxorubicin resistance in a TNBC xenograft tumor model." (PMID 31338333, 2019). "Univariate analysis showed that TUFT1 expression was positively correlated with tumor size, histological grade, axillary lymph node metastasis, and Rab5-GTP and Rac1-GTP expression (p = 0.024, p = 0.009, p = 0.000, p = 0.000, and p = 0.029, respectively)." (PMID 31572059, 2019). "Mechanism studies showed that TUFT1 promoted tumor cell metastasis and stemness by up-regulating the Rac1/β-catenin pathway." (PMID 31338333, 2019). "The level of TUFT1 protein was positively correlated with tumor size, histological grade and axillary lymph node metastasis (p = 0.010, p = 0.005, and p = 0.010, respectively)." (PMID 31338333, 2019). "Here, we demonstrated that TUFT1 knockdown can reverse taxotere resistance in a TNBC xenograft tumor model." (PMID 31572059, 2019). "Our observations indicate that TUFT1 is a key regulator of the mTORC1 pathway and suggest that it is a promising therapeutic target or a biomarker for tumor progression." (PMID 29423269, 2018). "When A549 cells were xenografted onto nude mice, knockdown of TUFT1 decreased the tumor volume, and it was rescued by wild-type TUFT1." (PMID 29423269, 2018). "Our investigations also highlighted the importance of TUFT1 in tumor growth and metastasis both in vitro and in vivo." (PMID 29423269, 2018).
tumor (continued). "TUFT1 is expressed in the morula, embryonic stem cells, soft tissues, such as brain (especially in neurons), kidneys, adrenal gland, liver, testis, and tumor cells." (PMID 29088838, 2017). "The increased expression of TUFT1 was shown to be positively correlated with tumor size, histological grade, lymph node metastasis (P = 0.010, P =0.000, P =0.000, respectively)." (PMID 29088838, 2017). "Here we showed that TUFT1 overexpression is positively correlated with tumor size, histological grade, and the rate of lymph node metastasis." (PMID 29088838, 2017). "In HCC, it promotes tumor cell proliferation and invasion by modulating the miR-34a-5p/TUFT1 axis." (PMID 40255398, 2025). "Similarly, TUFT1 has also shown to enhance tumor cell growth and migration in HCC through the same signaling pathway." (PMID 34257606, 2021). "In this study TUFT1 knockdown minimized the promoting effects of hypoxia on tumor growth and metastasis, suggesting that TUFT1 may represent a new potential therapeutic target for HCC treatment." (PMID 30970564, 2019). "Moreover, reduced TUFT1 expression restrained tumor growth compared with the control group in vivo." (PMID 29088838, 2017). "As a secreted acid-phosphorylated glycoprotein, Tuftelin 1 (TUFT1) is pathologically overexpressed during hepatocarcinogenesis and highly correlated with poor patient survival and aggressive tumor phenotypes." (PMID 41179299, 2025). "Altogether, our results provide evidence for the prevention of tumor angiogenesis through the repression of PEA15, PPP1CA and TUFT1 demonstrating the importance of their downregulation by miR-449a-5p." (PMID 34976171, 2022). "Our previous study demonstrated that TUFT1 was a critical oncogene in HCC and facilitated tumor growth and metastasis by activating the AKT pathway." (PMID 32908135, 2020). "Furthermore, bulk RNA sequencing indicated that knocking down TUFT1 altered the TGF-β transcriptome of HSCs and suppressed HSC expression of tumor-promoting factors." (PMID 41593321, 2026). "Furthermore, TUFT1 over-expression also rescued stemness-like properties in BACE1-AS knockout SW620 cells analyzed by the number and size of formed tumor spheres." (PMID 37986103, 2023). "Furthermore, subcutaneous xenograft model was established by injecting TUFT1 knockdown or control HCC cells, and the results showed that HCC tumor growth in vivo was also inhibited by TUFT1 knockdown." (PMID 35769513, 2022). "Regulation of mTORC1 signaling by TUFT1-RABGAP1 may thus be a factor that links vesicular trafficking and tumor progression." (PMID 29423269, 2018). "Tuftelin 1 (TUFT1), which plays an important role in the initial stages of the mineralization of ectodermal enamel, is widely expressed in different embryonic and adult tissues and some tumor cells." (PMID 29088838, 2017). "LINC01123 has emerged as a pivotal regulator in various types of cancer, exerting significant influence on tumor cell malignancy through intricate molecular mechanisms.For example, in OSCC and HCC, LINC01123 acts as a ceRNA by sequestering miR-34a-5p, which in turn upregulates TUFT1 expression." (PMID 40255398, 2025). "To evaluate whether TUFT1 expression can directly contribute to resistance to chemotherapy in TNBC, we used MDA-MB-231-shTUFT1 cells (or control MDA-MB-231 cells) in a xenograft tumor model." (PMID 31338333, 2019). "Because TUFT1 can promote proliferation and metastasis and inhibit apoptosis in MDA-MB-231 cells, to evaluate whether TUFT1 expression directly contributes to chemotherapy resistance in TNBC, we used MDA-MB-231-shTUFT1 cells and control MDA-MB-231 cells to generate a xenograft tumor model." (PMID 31572059, 2019).